PSMC3IP (PSMC3 interacting protein)
Description:
Plays an important role in meiotic recombination. Stimulates DMC1-mediated strand exchange required for pairing homologous chromosomes during meiosis. The complex PSMC3IP/MND1 binds DNA, stimulates the recombinase activity of DMC1 as well as DMC1 D-loop formation from double-strand DNA. This complex stabilizes presynaptic RAD51 and DMC1 filaments formed on single strand DNA to capture double-strand DNA. This complex stimulates both synaptic and presynaptic critical steps in RAD51 and DMC1-promoted homologous pairing. May inhibit HIV-1 viral protein TAT activity and modulate the activity of proteasomes through association with PSMC3. Acts as a tissue specific coactivator of hormone-dependent transcription mediated by nuclear receptors.
Synonyms: HOP2; TBPIP; GT198; HUMGT198A; ODG3
Tractability: PROTAC: ubiquitination databases record sites on it.
Gene: Protein-coding gene on chromosome 17 (42,572,310 to 42,577,831, reverse strand). Ensembl gene ENSG00000131470.
Subcellular location: Nucleus
Subcellular location (Human Protein Atlas): Nucleoplasm
Pathways (Reactome):
Reproduction: Meiotic recombination
Gene Ontology:
Molecular function: protein binding; transcription coactivator activity; double-stranded DNA binding; recombinase activator activity
Biological process: homologous chromosome pairing at meiosis; reciprocal meiotic recombination; meiotic joint molecule formation; meiotic strand invasion involved in reciprocal meiotic recombination; positive regulation of DNA-templated transcription
Cellular component: nucleoplasm; condensed nuclear chromosome; DNA recombinase auxiliary factor complex; nucleus
Genetic constraint (gnomAD): Loss-of-function variants: 26 observed, 36.78 expected, observed/expected ratio (o/e) 0.71, 90% interval 0.52 to 0.98. The upper end of that interval is the gene's LOEUF score, 0.98, which puts it in group 4 of 6, group 1 being the genes least tolerant of losing a copy. Missense variants: 250 observed, 280.16 expected, observed/expected ratio (o/e) 0.89, 90% interval 0.8 to 0.99. Synonymous variants: 87 observed, 103.97 expected, observed/expected ratio (o/e) 0.84, 90% interval 0.7 to 1.
Homologues: Orthologues: chimpanzee PSMC3IP (99% identical), macaque PSMC3IP (98% identical), dog PSMC3IP (94% identical), pig PSMC3IP (92% identical), rabbit PSMC3IP (88% identical), mouse Psmc3ip (88% identical), rat Psmc3ip (88% identical), guinea pig PSMC3IP (81% identical), tropical clawed frog psmc3ip (66% identical), zebrafish psmc3ip (63% identical).
Diseases named in the same sentence as PSMC3IP in open-access papers:
PSMC3IP is named in the same sentence as 24 diseases in open-access papers, as found by Europe PMC text mining. Sharing a sentence is not in itself a finding about the gene and the disease. The quoted sentences say what the papers report.
ovarian carcinoma (7 papers, 2015 to 2022). A malignant neoplasm originating from the surface ovarian epithelium. "The human GT198 gene (PSMC3IP; encodes GT198, also known as Hop2 or TBPIP) is a DNA repair gene and also a breast and ovarian cancer gene located within the BRCA1 locus at chromosome 17q21." (PMID 28881671, 2017). "In addition, Psmc3ip (also known as GT198) is used as a unique tumor marker suppressor gene for the mutant cells in ovarian cancer." (PMID 36080362, 2022).
Primary amenorrhea (4 papers, 2023 to 2024). "The pathogenic variant in PSMC3IP (c.600_602del, p.Glu201del) in POI was first reported in 2011 in five females in a Palestinian family, all of whom were homozygous carriers with primary amenorrhea and undetectable ovaries." (PMID 38737775, 2023). "This could be explained by the fact that pathogenic variants in these genes (for instance STAG3, MCM8 or PSMC3IP) result most often in severe changes in the maintenance of the ovarian reserve and cause a rapid loss of ovarian function, resulting in POI and primary amenorrhea." (PMID 39595984, 2024).
Azoospermia (3 papers, 2023). Absence of any measurable level of sperm,whereby spermatozoa cannot be observed even after centrifugation of the semen pellet. "Recently, another homozygous variant in PSMC3IP was reported in a consanguineous Yemeni family of four sisters with ovarian dysgenesis and a brother with azoospermia." (PMID 37988663, 2023). "The psmc3ip gene is essential for homologous recombination during meiotic division, and deficiency of psmc3ip results in azoospermia." (PMID 38067041, 2023). "The segregation of pathogenic loss of function variants in PSMC3IP, NR5A1, and STAG3 with POI in 13 female carriers and non-obstructive azoospermia (NOA) in three male carriers in the studied pedigrees suggested a significant role of these variants in infertility in both genders." (PMID 38737775, 2023).
head and neck squamous cell carcinoma (2 papers, 2021 to 2024). A squamous cell carcinoma that arises from any of the following anatomic sites: lip and oral cavity, nasal cavity, paranasal sinuses, pharynx, larynx, and salivary glands. "It is reported that Oct4 promotes stemness in head and neck squamous cell carcinoma via modulating PSMC3IP and RAD54L." (PMID 38430256, 2024).
Infertility (2 papers, 2021 to 2023). "Three studies report infertility in 3 males, all of whom were carriers of the pathogenic variants reported (PSMC3IP, NR5A1, and STAG3 variants)." (PMID 38737775, 2023).
oral cancer (2 papers, 2017 to 2021). "We have previously identified GT198 (gene symbol PSMC3IP, also known as Hop2) as an oncoprotein that induces tumor angiogenesis in human cancers, including oral cancer." (PMID 34476412, 2021).
hepatocellular carcinoma (1 paper, 2021). A malignant tumor that arises from hepatocytes.
triple-negative breast carcinoma (1 paper, 2015). An invasive breast carcinoma which is negative for expression of estrogen receptor (ER), progesterone receptor (PR), and human epidermal growth factor receptor 2 (HER2). "Our results show that PSMC3IP and EPSTI1 are able to modulate the extrinsic apoptotic pathway in estrogen receptor positive and triple negative breast cancer cell lines, highlighting them as potential therapeutic targets." (PMID 25590583, 2015).
tumor (10 papers, 2013 to 2024). "GT198 (PSMC3IP or Hop2), an oncoprotein encoded by a DNA repair gene, is overexpressed in tumor vessels." (PMID 39796646, 2024). "Human GT198 (PSMC3IP or Hop2) is an oncoprotein encoded by a DNA repair gene that is overexpressed in tumor stromal vasculature to stimulate the expression of angiogenic factors." (PMID 28881671, 2017). "Knockdown of Oct4 A isoform reduced self-renewal capacity in HNSCC and led to partial tumor cell radiosensitization caused by transcriptional downregulation of the cell cycle checkpoint kinases CHK1 and WEE1 and homologous recombination (HR) repair genes PSMC3IP and RAD54L." (PMID 34079088, 2021). "The potential role of PSMC3IP and RAD54L in tumor development is supported by significantly higher expression levels of these genes in HNSCC than in normal tissues." (PMID 34079088, 2021). "A set of genes including PRPF38A, RIOK3, QSER1, PSMC3IP, ATAD3B, MGC12982, and C20ORF27 were significantly overexpressed in HCC-R tumor tissue with fold changes ≥4 (P = 0.001 to 0.0001)." (PMID 24377043, 2013).
cancer (6 papers, 2017 to 2023). A tumor composed of atypical neoplastic, often pleomorphic cells that invade other tissues. "For instance, seven PSM genes (i.e. PSMA1, PSMA4, PSMC1, PSMC3IP, PSMD13, PSMG2-3 (PSM class I/II/V)) were overexpressed in the majority of the 16 cancer types." (PMID 36123629, 2022). "Today, the alias names in the literature include GT198 in cancer studies, Hop2 or TBPIP in biochemical studies, and PSMC3IP in genetic studies." (PMID 34476412, 2021).
PSMC3IP also shares sentences with these, for which no sentence is quoted: breast carcinoma (3 papers); leiomyoma (2); ovarian dysgenesis (2); breast tumor (1); cyst (1); fallopian tube cancer (1); glioma (1); infection (1); keloid (1); lymph node metastasis (1); melanoma (1); non-small cell lung carcinoma (1); Osteopenia (1); osteoporosis (1).